KLF9 (KLF transcription factor 9)
Diseases named in the same sentence as KLF9 in open-access papers (continued):
Sharing a sentence is not in itself a finding about the gene and the disease.
tumor (continued). "In conclusion, our findings indicate that ACTA2-AS1 may function as a tumor suppressor in PTC, at least partly by regulating miR-4428-dependent KLF9 expression as demonstrated in the graphical abstract." (PMID 38195623, 2024). "Krüppel-like Factor-9 (KLF9) and Krüppel-like Factor-13 (KLF13) are highly related proteins that function as inducers and/or repressors of specific target gene repertoires in a variety of tissues and in diverse pathophysiological states, including neoplasia." (PMID 38067370, 2023). "In snRNA-seq data, KLF9 is not significantly differentially expressed between ccRCC tumor cells vs. PT cells." (PMID 36973268, 2023). "It is therefore tempting to speculate that the down regulation of KLF9 and/or KLF13 in pre-neoplastic cells leads, in turn, to synergistic inductions in KLF16 expression and consequent tumor promotion." (PMID 38067370, 2023). "When analyzing survival outcomes, patients with negative KLF9 expression in their PDAC tumor cells saw a marked decrease in mean survival time (14.17 months) relative to patients who were positive for KLF9 expression (23.95 months)." (PMID 37239940, 2023). "Finally, we verified that the expression levels of KLF9, MCM2, INHBA, and CGREF1 were related to age, tumor stage, and differentiation and were closely related to the prognosis of young CRC patients." (PMID 37370046, 2023). "In this article, we summarize the work that has identified the roles of KLF9 (and to a lesser degree KLF13) in tumor suppression or promotion via unique effects on differentiation, pro- and anti-inflammatory pathways, oxidative stress, and tumor immune cell infiltration." (PMID 38067370, 2023). "Clearly, we do not know enough about the specifics of KLF9 and KLF13 actions in the tumor immune cell microenvironment, a deficiency that should be rectified." (PMID 38067370, 2023). "Interestingly, KLFs can exert opposite effects in regulating the same pathways and initiate different cell responses, as some of them can function as tumor suppressors (KLF2, KLF8) and some as oncogenes (KLF7, KLF9)." (PMID 37239940, 2023). "Both KLF9 and DAB2IP were reported to be tumor suppressors in many tumors." (PMID 34116691, 2021). "KLF9 and its role in cancer has not been extensively investigated, although some studies have suggested KLF9 plays a tumor-suppressive role." (PMID 34265306, 2021). "A downregulated expression of KLF9 was suggestively found in the lower stage tumor group (0.68 ± 1.6) and the non-metastatic group (0.13 ± 1.82)." (PMID 35047407, 2021). "Combining KLF9 expression restoration with PI3K/Akt pathway inhibition may yield synergistic therapeutic effects to counteract pathway dysregulation, while its biomarker potential warrants validation in PI3K/Akt-driven tumor subtypes." (PMID 40860800, 2025). "Notably, we found that KLF9 and INHBA were associated with prognosis in EOCRC but not in LOCRC, while the expression differences in KLF9, MCM2, and INHBA between the tumor and normal groups were more obvious in EOCRC than in LOCRC." (PMID 37370046, 2023). "None of these drugs synergized with KLF9 to kill tumor cells as measured by MTS assays." (PMID 30348136, 2018). "In addition, to increase the robustness of our analysis, we selected KLF9 as a second potential target as it was identified as downregulated by YAP in an independent study conducted in MCF-10A cells and previously suggested to have tumor-suppressive activities." (PMID 34265306, 2021). "Another research verifies this by revealing that the absence of KLF9 inhibits PGR and FOXO signaling in endometrial cells, boosting oncogenesis and Tumor spread." (PMID 37833790, 2023). "The extent of KLF9 and KLF13 co-expression and co-functionality in tumor cells, as well as in the non-malignant cells residing within the tumor microenvironment, is another key question to be addressed." (PMID 38067370, 2023).
tumor (continued). "The roles (similar or different) of KLF9 and KLF13 in cancer stem cells and whether reductions or absence of KLF expression drives tumor cell metastasis also requires follow up." (PMID 38067370, 2023). "In addition, we found that KLF9 negatively regulates invasion and metastasis of HCC but not affecting cell growth or tumour growth." (PMID 37400979, 2023).
cancer (40 papers, 2014 to 2025). A tumor composed of atypical neoplastic, often pleomorphic cells that invade other tissues. "Future research should focus on validating KLF9’s diagnostic capabilities across various cancer types through large-scale clinical trials." (PMID 40860800, 2025). "The expression of KLF9 in CAFs has been linked to various regulatory mechanisms that modulate the behavior of these fibroblasts in the context of cancer." (PMID 40860800, 2025). "Such methylation dynamics at KLF9-associated sites were linked to immune- and cancer-related pathways." (PMID 40860800, 2025). "With the link between dysregulated hormone signaling, circadian disruption, and BCa progression, we then determined the contextual role of KLF9 in the hormone-circadian regulatory axis towards BCa progression through several cancer hallmark assays." (PMID 36823570, 2023). "Several recent studies have indicated that KLF9 is downregulated in various types of human cancers and associated with cancers tumorigenicity, proliferation and metastasis." (PMID 35501825, 2022). "This differential expression suggests that KLF9 could serve as a diagnostic marker, aiding in the identification of early-stage cancers before they progress to more advanced, less treatable stages." (PMID 40860800, 2025). "Further comparison of KLF9's function between different cancer types could help unveil the fundamental mechanisms of KLF9 underlying its functions in cancer cells." (PMID 37400979, 2023). "Furthermore, KLF9 has been implicated in the regulation of genes involved in cellular responses to environmental stimuli, and its expression is often correlated with changes in DNA methylation patterns in various cancers, including papillary thyroid carcinoma." (PMID 40860800, 2025). "Thus, there is a pattern emerging for the associations of KLF9 with cell, tissue, and somatic stress responses: the latter are themselves implicated in cancer development, as well as in determining the efficacy of cancer treatments." (PMID 38067370, 2023). "Moreover, recent evidence has suggested that KLF9 is associated with cancer cell proliferation." (PMID 35501353, 2022). "KLF9’s expression patterns show significant correlation with patient prognosis across various cancer types, with low expression often indicating poor outcomes, highlighting its potential as a prognostic biomarker." (PMID 40860800, 2025). "Overall, the present review provides new insights and perspectives for future research on KLF9 in cancer, underscoring its importance in personalized medicine." (PMID 40860800, 2025). "Firstly, there is significant heterogeneity in the expression of KLF9 across different types of cancer." (PMID 40860800, 2025). "Clinically, KLF9 emerges as a potential prognostic biomarker due to its differential expression patterns across various cancer types, with lower KLF9 levels often correlating with poorer patient outcomes." (PMID 40860800, 2025). "The multifaceted roles of KLF9 in cancer, as outlined in this review, underscore its potential as a pivotal therapeutic target and prognostic biomarker." (PMID 40860800, 2025). "In this section, a comprehensively review of the functional significance of KLF9 across major cancer types is conducted." (PMID 40860800, 2025). "Although previous studies have shown that KLF9 has potential biomarker and target value in cancer prognosis and treatment, there are still many challenges in its clinical translation process." (PMID 40860800, 2025). "KLF9 holds huge potential as a marker for early cancer diagnosis, especially considering its role in regulating cell proliferation, apoptosis, and metastasis." (PMID 40860800, 2025). "KLF9, the increased expression of which has been reported to have an inhibitory effect on cancer, has been used for therapeutic purposes in various cancer types." (PMID 38627780, 2024). "The data clearly indicate that KLF9-overexpression significantly enhanced paclitaxel anti-cancer properties." (PMID 37111314, 2023).
cancer (continued). "We observed a decrease in KLF9 mRNA level in 34 of 43 (79.1%) HCC cancer samples compared to their paired normal tissues." (PMID 37400979, 2023). "One important physiological context for cancer pre-disposition in which KLF9 and KLF13 are known to intersect in function is adipogenesis." (PMID 38067370, 2023). "To further investigate the mechanism that regulates the expression of KLF9 in cancer, we again turned to the ChIP‐seq database to look for possible transcription factors that can bind to the regulatory regions of the KLF9." (PMID 37400979, 2023). "Expression of KLF9 was lower in advanced-stage cancers, those with distant metastasis, and lower-stage tumors without metastasis compared to controls." (PMID 37833790, 2023). "KLF9 promotes apoptosis of cancer cells, especially androgen-dependent cells, in PC by severely suppressing the activation of AKT and its downstream targets and inhibiting the androgen receptor pathway." (PMID 36761967, 2023). "Among all the important features of cancer cells, we specifically identified that KLF9 suppresses HCC metastasis, the deadliest stage of this disease." (PMID 37400979, 2023). "The known associations of KLF9 and KLF13 with cancers in humans (and relevant mouse models) are summarized below." (PMID 38067370, 2023). "First, the top 20 regulatory transcription factor TFs in human cancers were identified using the Cistrome DB toolkit, and KLF9 was found to have the greatest regulatory potential." (PMID 36386179, 2022). "The nuclear protein Krüppel-like factor 9 (KLF9) suppresses development of cancers in multiple tissues including the liver." (PMID 35406507, 2022). "Patients with multifocal cancer had increased KLF9 expression than with patients unifocal cancer (p < 0.01)." (PMID 36186479, 2022). "For instance, miR-140 is highly expressed in certain cancers and promotes cell proliferation, migration, and invasion via its regulation of autophagy and KLF9 levels." (PMID 34479600, 2021). "This highlights the potential of small molecule therapies to exploit KLF9’s regulatory roles in cancer and other diseases, paving the way for new treatment paradigms that could be rapidly translated into clinical settings." (PMID 40860800, 2025). "Therefore, future research should prioritize elucidating the specific mechanisms that govern KLF9’s behavior in distinct cancer types and stages." (PMID 40860800, 2025). "Bridging these mechanistic insights with translational efforts could unlock KLF9’s full potential as a linchpin in next-generation cancer therapeutics." (PMID 40860800, 2025). "Expression profiles, molecular mechanisms, and clinical implications of KLF9 in various cancers." (PMID 40860800, 2025). "Kruppel-like factor 9 (KLF9) is a transcription factor that has gained significant attention in recent years for its critical involvement in development and progression of various cancers." (PMID 40860800, 2025). "Similarly, other lncRNAs have been identified to interact with KLF9 and influence its transcriptional activity in various cancer contexts, highlighting the intricacy of regulatory networks involving KLF9 and non-coding RNAs." (PMID 40860800, 2025). "The expression level of KLF9 is closely related to the occurrence of cancer." (PMID 40860800, 2025). "Furthermore, KLF9 interacts with microRNAs to further promote immune evasion by enhancing the proliferation and invasiveness of cancer cells." (PMID 40860800, 2025). "The discovery of this mechanism not only reveals KLF9’s context-dependent role in cancer progression but also positions it as a promising therapeutic target, offering potential strategies to reverse macrophage-mediated immunosuppression and combat NPC metastasis through selective pathway modulation." (PMID 40860800, 2025). "This comprehensive review aims to consolidate recent advances in KLF9 research, which could facilitate the development of personalized medicine approaches for cancer patients." (PMID 40860800, 2025).
cancer (continued). "KLF9 was identified as one of 13 transcription factors (TFs) exhibiting significant correlations with localized DNA demethylation at their binding sites across 19 cancer types." (PMID 40860800, 2025). "In cancer tissues, KLF9 expression was low, and PAFAH1B3 expression was high." (PMID 38649699, 2024). "While this repressive effect of KLF9 has, so far, been demonstrated solely for this cancer type, the findings may be relevant to other cancer type(s) and other KLF family members." (PMID 38067370, 2023). "Since adipogenesis underlies obesity and consequent adipocytokine secretion, and several adipocytokines are cancer-promoting (e.g., leptin), KLF9 and KLF13 may significantly affect cancer pre-disposition indirectly through their targeted actions on fat depots." (PMID 38067370, 2023). "Moreover, the oncogenic miR-636, targeting the 3′-UTR of KLF9 mRNA, inhibited KLF9 expression in these cancer lines." (PMID 38067370, 2023). "KLF9-dependent ROS repression may be crucial for cancer progression as ROS levels are higher in cancer due to increased metabolic activity." (PMID 37111314, 2023). "Similarly, a decrease in KLF9 protein level was also found in HCC cancer tissues compared to paired normal tissues as shown by western blot." (PMID 37400979, 2023). "On the other hand, a few studies reported that KLF9 was tightly involved in cancer." (PMID 35399713, 2022). "Furthermore, we confirmed that de novo methylation is precluded across cancers at CpGs lying in genomic regions enriched for TF binding signatures associated with SP1, CTCF, NRF1, GABPA, KLF9, and/or YY1." (PMID 35440061, 2022). "Furthermore, KLF9-induced apoptosis has been found to be regulated by oxidative stress in cancer cells via NRF2, as has been found in the current study." (PMID 34008050, 2021). "Evidence for the involvement of KLF9 in cancer was provided by previous studies." (PMID 31821171, 2019). "First, compared to undifferentiated stem-like cells that are more resistant to chemotherapeutic drugs, differentiated cells induced by KLF9 expression may be more vulnerable to anti-cancer drugs, such as HDAC inhibitors." (PMID 30348136, 2018). "Nevertheless, the identification of KLF9 and the initial results showing its inhibitory effect on cancer cell invasion, corroborated by its differential expression between invasive and non-invasive cell lines, imply interactions between proliferation- and invasion-mediating programs." (PMID 25593984, 2014). "Furthermore, KLF9 represents a promising therapeutic target, as modulating its activity may offer new strategies for cancer treatment." (PMID 40860800, 2025). "This means that KLF9 may have different biological functions and clinical significance in different types of cancer or different stages of the same type, therefore individualized strategies are needed to evaluate the effectiveness of KLF9 as a biomarker for different types of cancer." (PMID 40860800, 2025). "Besides, the integration of KLF9 expression profiling with other biomarkers could enhance the accuracy of early cancer detection, ultimately leading to improved patient outcomes." (PMID 40860800, 2025). "Interestingly, KLF9 may employ analogous mechanisms to enforce localized hypomethylation, positioning it as a key epigenetic regulator in cancer pathology." (PMID 40860800, 2025). "Moreover, the ability of KLF9 to inhibit cell growth and induce apoptosis in cancer cells highlights its potential as a therapeutic target, which could be leveraged for early intervention strategies." (PMID 40860800, 2025). "Finally, we validated the clinical relevance of KLF9 in live cancer using clinical tissue samples." (PMID 37400979, 2023). "Moreover, KLF9 targets significant signaling pathways in various cancers." (PMID 37833790, 2023). "Therefore, it is possible that miR-300 promotes cancer progression by suppressing KLF9." (PMID 35501353, 2022).